IDH3A (isocitrate dehydrogenase (NAD(+)) 3 catalytic subunit alpha)
Diseases named in the same sentence as IDH3A in open-access papers:
IDH3A is named in the same sentence as 44 diseases in open-access papers, as found by Europe PMC text mining. Sharing a sentence is not in itself a finding about the gene and the disease. The quoted sentences say what the papers report.
glioma (6 papers, 2017 to 2023). A benign or malignant brain and spinal cord tumor that arises from glial cells (astrocytes, oligodendrocytes, ependymal cells). "This demonstrated that DNMT1, IDH3A, TACC3, and TKT could be incorporated as prognostic markers for glioma." (PMID 37875819, 2023). "In contrast, expression levels of enzymes involved in downstream metabolism of isocitrate, including IDH1, IDH2 and IDH3A, α-KGDH, succinate dehydrogenase (SDHB), fumarate hydratase (FH) and malate dehydrogenase (MDH2), were remarkably lower in IDH1MUT glioma versus IDH1WT glioma." (PMID 28467784, 2017).
retinal degeneration (6 papers, 2018 to 2024). Degeneration of the retina. "The loss of Idh3a in mice is embryonically lethal, and the mouse Idh3a E229K mutation leads to an early and rapid retinal degeneration." (PMID 35985423, 2022). "Loss of Idh3a in mice is embryonic lethal, but mice with Idh3a E229K mutation exhibits retinal degeneration." (PMID 35985423, 2022). "It was shown that human IDH3A and IDH3B mutations are associated with severe early childhood-onset retinitis pigmentosa, and mouse Idh3a mutations lead to retinal degeneration." (PMID 35360866, 2022). "Some mutations in the mitochondrial aconitase gene (ACO2), similar to IDH3A, can result in severe neurological disease, progressive optic atrophy and retinal degeneration, whilst other mutations in the same gene can give optic atrophy only." (PMID 30478029, 2018). "We have identified a missense mutation, E229K, in mouse Idh3a, which is associated with late-onset retinal degeneration." (PMID 30478029, 2018). "Mutations of IDH3A and IDH3B are identified in patients with inherited retinal degeneration, pseudocoloboma, and epileptic encephalopathy." (PMID 35985423, 2022). "Patients with IDH3A mutations showed an early onset (1–11 years old) of retinal degeneration, and patients with IDH3B mutation showed a late onset (30–50 years old) of retinal degeneration." (PMID 35985423, 2022). "Biallelic recessive variants in the a and b genes, IDH3A and IDH3B, induce retinal degeneration and encephalopathy." (PMID 33426505, 2020). "We considered the missense mutation, E229K, in Idh3a to be the likely causative mutation, as human patients with mutations in either IDH3A or IDH3B exhibit retinal degeneration." (PMID 30478029, 2018). "Loss-of-function and missense mutations in both IDH3A and IDH3B have previously been implicated in families exhibiting retinal degeneration." (PMID 30478029, 2018). "Another study showed retinal degeneration and mitochondrial dysfunction in Idh3a-mutant mice, but no other detectable abnormal phenotypes were observed." (PMID 38275411, 2024). "In contrast to Idh3a mutants, Idh3b mutant mice are fully viable and show no signs of retinal degeneration within 6 months of age." (PMID 30478029, 2018).
breast carcinoma (3 papers, 2020 to 2022). "Abnormal IDH3A expression was associated with the poor OS of lung and breast cancer patients, promoting tumor growth by inducing HIF-1-mediated metabolic reprogramming and angiogenesis." (PMID 35359394, 2022). "Upon cholesterol treatment, there is a significant increase in the expression of metabolic target genes of ERRα, including IDH3A, VEGF, PDK4, SOD2, GSTM1, and SPP1, in breast cancer cells." (PMID 32717915, 2020). "It is thus significant that cholesterol binding to ERRα and cholesterol-mediated increase in ERRα-PGC-1α interaction result in increased expression of ERRα itself and its metabolic target genes including IDH3A, VEGF, SOD2, GSTM1, PDK4, SPP1 in breast cancer cells." (PMID 32717915, 2020).
glioblastoma (3 papers, 2013 to 2024). The most malignant astrocytic tumor (WHO grade IV). "Recently, a study reported that IDH3A could regulate one-carbon metabolism in glioblastoma via the IDH3A-cSHMT signaling axis, promoting cancer progression through metabolic reprogramming." (PMID 35359394, 2022). "Many of the genes identified through this meta-analysis have in fact been implicated in development of astrocytoma including EGFR (amplification occurs in ∼40% of primary glioblastomas, HIF-1α, MYC, WNT5A, and IDH3A." (PMID 23737970, 2013).
Mitochondrial encephalopathy (3 papers, 2022 to 2025). "Furthermore, we hypothesize that the infantile encephalopathy, along with cognitive and motor decline observed in Patient 1 may be attributed to a mitochondrial encephalopathy caused by mutations in the IDH3A gene." (PMID 40244231, 2025).
Retinal dystrophy (2 papers, 2021 to 2023). Retinal dystrophy is an abnormality of the retina associated with a hereditary process. "ArRP is an inherited form of retinal dystrophy caused by inherited or acquired mutations in over 50 different genes, including IDH3A." (PMID 33986196, 2021).
retinitis pigmentosa 90 (2 papers, 2024 to 2025). "The biallelic variants in the IDH3A gene are associated with retinitis pigmentosa 90 (#619007) in Online Mendelian Inheritance in Man (OMIM)." (PMID 39026936, 2024). "Recent findings indicate that disease-causing variants in the IDH3A gene are increasingly associated with autosomal recessive retinitis pigmentosa 90 (RP90) and Leber congenital amaurosis (LCA), with or without macular pseudocoloboma." (PMID 40244231, 2025). "Disease-causing variants in the IDH3A gene are associated with autosomal recessive retinitis pigmentosa 90 (RP90) and Leber congenital amaurosis, with or without macular pseudocoloboma." (PMID 40244231, 2025).
acute leukemia (1 paper, 2022). A clonal (malignant) hematopoietic disorder with an acute onset, affecting the bone marrow and the peripheral blood. "Further analysis using clinical datasets demonstrated that the elevated expression of a three-gene signature, consisting of SDHA, IDH3A, and ANXA11, was significantly associated with poor survival of acute leukemia patients." (PMID 35463978, 2022).
asthenozoospermia (1 paper, 2024). "The observed protein expression changes in ChAcDel/Del mice, particularly the increase in TOM20 and the decreases in IDH3A and ACAT1, offer insights into the molecular mechanisms underlying the mitochondrial dysmorphology and asthenozoospermia in these mice." (PMID 38275411, 2024).
astrocytoma (1 paper, 2013). "Many of the genes have in fact been implicated in development of astrocytoma, including EGFR, HIF-1α, c-Myc, WNT5A, and IDH3A." (PMID 23737970, 2013).
B cell lymphoma (1 paper, 2016). "Notably, re-evaluation of expression profiling data following acute TTP expression in Myc-driven B cell lymphoma found that mRNAs encoding the metabolic enzymes Dlat, Idh3a, Gpd2, and Cycs are also rapidly down-regulated targets of TTP in this context (data not shown)." (PMID 27825143, 2016).
Infantile encephalopathy (1 paper, 2025). Encephalopathy with onset in the infantile period. "In addition, a homozygous missense variant, IDH3A c.911C>A, p.(Pro304His), has been identified through exome sequencing in a patient with severe infantile encephalopathy and RP." (PMID 40244231, 2025). "In contrast, specific variants of IDH3A have been implicated in macular pseudocoloboma and severe infantile encephalopathy, conditions affecting tissues such as the macula and brain, which are highly metabolically active and, therefore, particularly vulnerable to energy deficits." (PMID 40244231, 2025).
Insulin resistance (1 paper, 2019). Increased resistance towards insulin, that is, diminished effectiveness of insulin in reducing blood glucose levels. "Serine hydroxymethyltransferase 1 (SHMT1), ALDOC, SDSL, ASS1, and IDH3A are novel biomarkers for the development of insulin resistance." (PMID 30678306, 2019).
ischemia (1 paper, 2022). A hypoperfusion of the BLOOD through an organ or tissue caused by a PATHOLOGIC CONSTRICTION or obstruction of its BLOOD VESSELS, or an absence of BLOOD CIRCULATION. "This is the case of SUCLA2 and DLD, which were down-regulated during ischemia and not recovered after revascularization, and the isocitrate dehydrogenase components IDH3A and IDH2, which were found to be down-regulated after the re-establishment of coronary blood flow." (PMID 35216205, 2022).
lung adenocarcinoma (1 paper, 2019). A carcinoma that arises from the lung and is characterized by the presence of malignant glandular epithelial cells. "In summary, high expression of IDH3a in lung adenocarcinoma patients is associated with higher glucose uptake." (PMID 31355526, 2019). "IDH3a targets AKT‐GLUT1 pathway to affect glucose uptake and metabolites in lung adenocarcinoma." (PMID 31355526, 2019).
lung carcinoma (1 paper, 2018). "Additionally, IDH3A promotes tumor growth by activating hypoxia-inducible factor 1 (HIF-1) and promotes the stability of HIF-1 in participating in angiogenesis and is also associated with poor survival in lung cancer." (PMID 29486777, 2018).
Macular dystrophy (1 paper, 2024). Macular dystrophy is a nonspecific term for retinal degeneration, generally confined to the macula, usually presumed of genetic origin. "A re-evaluation of the RGS data with additional HPO terms, that is, “(HP:0007754) macular dystrophy,” led to the identification of a homozygous candidate variant in the IDH3A gene (ENST00000299518.7, c.802G>A, p.Gly268Arg) (OMIM:601149)." (PMID 39026936, 2024).
major depressive disorder (1 paper, 2016). An episode of depression lasting two or more weeks without an intervening episode of mania. "Results showed that protein levels of IDH3A in the cerebellum from BD (P=0.017), major depressive disorder (P=0.006) and schizophrenia (P=0.001) were significantly lower than in controls." (PMID 26782057, 2016). "We did find reduced expression of IDH3A protein in the cerebellum in BD and other psychiatric disorders such as major depressive disorder and schizophrenia." (PMID 26782057, 2016). "We examined whether protein expression of IDH3A and IDH3B in the cerebellum and parietal cortex (BA7) differed between samples from patients with BD, major depressive disorder or schizophrenia, and controls." (PMID 26782057, 2016).
male infertility (1 paper, 2023). The inability of the male to effect fertilization of an ovum after a specified period of unprotected intercourse. "Among these were well-studied protein biomarkers for male infertility such as IDH3A, GAPDHS, FH, and DLAT." (PMID 36509450, 2023).
mesothelioma (1 paper, 2023). A usually malignant and aggressive neoplasm of the mesothelium which is often associated with exposure to asbestos. "Other highly expressed genes in sarcomatoid mesothelioma cell lines were two ATP synthase subunits (ATP5H, ATPO), MTCO2, COX5B, COX 6C2, IDH3A, IDH3B and TIMM9." (PMID 37297007, 2023).
night blindness (1 paper, 2025). Inability to see clearly in dim light. "Previous reports describing variants in the IDH3A gene across various families have consistently noted a relatively severe phenotype, with rapid progression from night blindness to complete vision loss." (PMID 40244231, 2025).
Stroke (1 paper, 2021). Sudden impairment of blood flow to a part of the brain due to occlusion or rupture of an artery to the brain. "Moreover, potential biomarkers like Syt1 and Idh3a could be considered to be applied in clinical practice for early identification of cold wave-related stroke among inpatients during cold waves, and prophylactic drugs like batroxobin for treatment of cold wave-related stroke." (PMID 34086602, 2021).
type 2 diabetes (1 paper, 2021). "The studies aimed at identifying heart metabolic shifts in a diet-induced pre-diabetic mice model and type 2 diabetes showed significantly downregulated IDH3a expression." (PMID 33498641, 2021).
tumor (18 papers, 2011 to 2024). "We also found the size of tumor was associated with IDH3a expression, suggesting that IDH3ɑ may affect tumor proliferation." (PMID 31355526, 2019). "IDH3a immunoreactivity that was readily detected in the cytoplasm of tumor cell was considered to be a positive result." (PMID 31355526, 2019). "This study was aimed to investigate the relationship between IDH3a expression and tumor glucose uptake." (PMID 31355526, 2019). "The aim of this study was to investigate the relationship between IDH3a expression and glucose uptake of tumor, and to explore and elucidate the involvement of IDH3a in the AKT pathway affecting glucose uptake by detecting GLUT1 and HK2." (PMID 31355526, 2019). "Next, we detected ERRα, IDH3A, c-Myc and Cyclin D1 expression by immunostaining pathological tissue sections of xenograft tumour." (PMID 30185207, 2018). "Here, we show for both the IDH2 and IDH3A/IDH3B genes expression is mainly correlated in tumor samples exhibiting deleted copy number to normal copy number." (PMID 22174824, 2011). "In contrast to IDH1 and IDH2, no tumour-associated mutations for any IDH3 genes (IDH3A, IDH3B and IDH3G) have been reported." (PMID 37296846, 2023). "Interestingly, IDH3A has been reported to localize in the nucleus and interact with transcriptional factors to promote tumor growth." (PMID 35985423, 2022). "The conclusion may be more convincing if it can be demonstrated that IDH3a interference or inhibitor can affect tumor glucose uptake in animal tumor model with [18F]‐FDG PET scanning." (PMID 31355526, 2019). "The downregulation of IDH3a affects the production of metabolite, we found lactate in the culture medium was reduced to a certain extent, while the ATP levels did not change significantly, which may be related to the compensatory mechanisms of tumor energy production." (PMID 31355526, 2019). "A number of mitochondrial proteins with relevance to tumour pathophysiology were altered, including BSG, SNCB and three Isocitrate dehydrogenase 3 forms (IDH3A, IDH3B, and IDH3G)." (PMID 24728830, 2014). "HBA, HBD and HCD2 positively correlated with high-grade gliomas; GFAP, PHP14, 6PGL, PSD13, PEA15, TPIS, CRYAB_b, IPYR and IDH3A correlated with low-grade tumors; on the other hand, NFM, CN37, NDUS1 and MDHC negatively correlated with tumor samples." (PMID 25050814, 2014). "Consistent with this premise, tumor cells most sensitive to these agents exhibit over expression of TCA-related discriminating genes, IDH3A, IDH1, IDH3G, ACO2 and ACLY." (PMID 23056181, 2012). "Differential expression of proteins was observed between stromal and tumor cells for ENO3, GLUT1, HK2, IDH3A, LDHA and PKM2." (PMID 22412968, 2012). "Network 3 was characterised by the insertion of a hub protein HNF4alpha, a transcription factor recently shown to play a role in other neoplasias and Network 4 was characterised by numerous mitochondrial-localised proteins (CAT, IDH3A, NDUFS3 and other complex 1 proteins, OXCT1 and PRDX3)." (PMID 24838487, 2014). "Several proteins, for example BSG (increased in GBM), SNCB (decreased in GBM) and IDH3 (with IDH3A, IDH3G and IDH3B all decreased in GBM), did not fall into an obvious functional grouping but are pertinent to tumour pathophysiology (see “Discussion” section)." (PMID 24728830, 2014).
cancer (9 papers, 2014 to 2022). A tumor composed of atypical neoplastic, often pleomorphic cells that invade other tissues. "IDH3A encodes an enzyme in the metabolic tricarboxylic acid (TCA) cycle that is frequently altered in cancer cells." (PMID 29486777, 2018). "High glucose-driven resistance in cancer cells was associated with elevated expression of metabolic enzymes HKII, PFK1, GAPDH, PKM2, LDH-A, IDH3A, and FASN." (PMID 34692517, 2021). "Conceivably, the IDH3A mechanism documented in cancer cells may play an important role in the normal development of the early post-hatch liver." (PMID 34030631, 2021). "In cancer cells, elevated levels of IDH3A ultimately lead to decreased levels of α-KG." (PMID 34030631, 2021). "IDH3A also acts in the conversion of metabolism that occurs with cancer fibroblasts." (PMID 29486777, 2018). "IDH3A, a major metabolic target gene of ERRα, is a key enzyme in the TCA cycle, and is known to stimulate angiogenesis and metabolic reprogramming of cancer cells to provide the necessary nutrients for cancer cell growth." (PMID 32717915, 2020). "Notably, two of the proteins, SDHA and IDH3A, key components of TCA, are involved in regulating energy metabolism in the mitochondria and considered to be actionable therapeutic targets in several cancers." (PMID 35463978, 2022).
infection (3 papers, 2022 to 2025). The state of being infected such as from the introduction of a foreign agent such as serum, vaccine, antigenic substance or organism. "It is most likely that the infection hampered the tricarboxylic acid (TCA) cycle, because several genes (such as Sdhaf3, Sucla2, Idh3a and Mdh2) encoded the key enzymes in TCA cycle were significantly downregulated." (PMID 36618398, 2022).
psychiatric disorder (1 paper, 2016). A disorder characterized by behavioral and/or psychological abnormalities, often accompanied by physical symptoms. "Thus, it is likely that IDH3A abnormalities may be involved in the pathogenesis of major psychiatric disorders." (PMID 26782057, 2016).
IDH3A also shares sentences with these, for which no sentence is quoted: neurological disease (2 papers); AIDS (1); demyelination (1); Encephalopathy (1); glaucoma (1); heart failure (1); hepatocellular carcinoma (1); Leber congenital amaurosis (1); leukemia (1); mammary adenocarcinoma (1); melanoma (1); neuroblastoma (1); optic atrophy (1); pancreatic adenocarcinoma (1); pancreatic cancer (1); retinitis pigmentosa (1); schizophrenia (1).